USP3 (ubiquitin specific peptidase 3)
Diseases named in the same sentence as USP3 in open-access papers (continued):
Sharing a sentence is not in itself a finding about the gene and the disease.
neuroblastoma (continued). "For this purpose, we first checked the expression of USP3 and REST in the SK-N-AS, SK-N-DZ, SH-SY5Y, and SK-N-SH neuroblastoma cell lines." (PMID 37170124, 2023). "ALYREF and MYCN form a transcriptional activator complex, which upregulates USP3 expression, promoting the growth and tumorigenicity of MYCN-amplified neuroblastoma cells." (PMID 37537569, 2023). "Next, we analyzed the deubiquitinating activity of USP3 on both endogenous and exogenous REST protein degradation in neuroblastoma and HEK293 cells, respectively." (PMID 37170124, 2023). "The final goal of this study was to elucidate the role of USP3 on REST protein degradation and its influence on self-renewal and differentiation of neuroblastoma." (PMID 37170124, 2023). "ALYREF-mediated upregulation of USP3 expression prevented MYCN protein degradation and resulted in increased neuroblastoma cell viability in vitro and in vivo." (PMID 37170124, 2023). "Silencing endogenous USP3 with USP3 siRNA-1 or USP3 siRNA-2 (lanes 2–3 and 5–6) in MYCN-amplified neuroblastoma cells significantly decreased MYCN protein expression." (PMID 33767157, 2021). "We saw significant positive correlations between USP3 and MYCN expression levels in neuroblastoma tissues." (PMID 33767157, 2021). "Duolink analysis confirmed the interaction between USP3 and REST by showing the fluorescence signals (PLA dots), but no PLA dots were observed when neuroblastoma cells were stained with either USP3 or REST antibody alone." (PMID 37170124, 2023). "In summary, our results suggest that the high expression of USP3 and REST may impair neuroblastoma differentiation, where neural crest cells lose the ability to differentiate into mature neurons." (PMID 37170124, 2023). "The correlation between USP3 and REST expression was assessed using patient neuroblastoma datasets." (PMID 37170124, 2023). "Moreover, co-IP analysis using antibodies against endogenous USP3 or REST demonstrated that endogenous USP3 interacts with REST protein and vice versa under the physiological conditions in neuroblastoma cells." (PMID 37170124, 2023). "Furthermore, a scatterplot of the USP3 and REST mRNA expression patterns obtained from the SEQC and TARGET datasets produced r-values of 0.317 and 0.217, respectively, suggesting a positive correlation between USP3 and REST in neuroblastoma tumors." (PMID 37170124, 2023). "Immunofluorescence staining demonstrated that the downregulation of USP3 resulted in a significant reduction in REST protein levels in SH-SY5Y, SK-N-SH and SK-N-DZ neuroblastoma cell lines." (PMID 37170124, 2023). "Additionally, it was shown that USP3 deubiquitinates MYCN, an oncoprotein observed in most neuroblastoma patients and considered as an indicator of tumor aggressiveness." (PMID 37170124, 2023). "The expression of USP3 and REST was found in all of the neuroblastoma cell lines tested." (PMID 37170124, 2023). "Together these data suggest MYCN and ALYREF bind together in a transcriptional coactivator complex to increase USP3 transcript levels, consequently reducing MYCN ubiquitination, and further increasing MYCN protein to the levels required to drive neuroblastoma tumorigenesis." (PMID 33767157, 2021). "The silencing of USP3 resulted in distinct morphological changes in SH-SY5Y, SK-N-SH and SK-N-DZ neuroblastoma cell lines, exhibiting a flatter and differentiated cell appearance with neurite-like processes compared to the scrambled-shRNA transfected neuroblastoma cells." (PMID 37170124, 2023). "Furthermore, a positive correlation between USP3 and REST expression was observed in neuroblastoma." (PMID 37170124, 2023). "Interestingly, the reduction in USP3 protein level is initiated much earlier than in REST protein, suggesting that down-regulation of USP3 might induce rapid differentiation of neuroblastoma by decreasing its substrate REST protein levels." (PMID 37170124, 2023).
glioblastoma (6 papers, 2020 to 2024). The most malignant astrocytic tumor (WHO grade IV). "The newly identified HOXA‐AS3/mir‐455‐5p/USP3 pathway offers important clues to understanding the key mechanisms underlying the action of lncRNA HOXA‐AS3 in glioblastoma." (PMID 32918360, 2020). "Clinicopathological data demonstrate that USP3 correlates with a shorter overall and relapse-free survival in glioblastomas." (PMID 32268558, 2020). "Similarly, during the progression of glioblastomas, USP3 stabilises Snail via deubiquitination, resulting in tumour proliferation, invasion and migration." (PMID 34930901, 2021). "This study improved our understanding of the HOXA‐AS3/miR‐455‐5p/USP3 signalling pathway and may facilitate future development of new treatments for glioblastoma." (PMID 32918360, 2020). "USP3 has been upregulated in glioblastoma multiforme (GBM), a lethal malignant brain tumor in adults." (PMID 37170124, 2023). "USP3 has the capability to interact with Claspin via the UCH domain for the purpose of deubiquitinating it, resulting in the activation of Claspin-dependent ATR-Chk1 signaling that ultimately contributes to the augmentation of glioblastoma radiation resistance." (PMID 38773075, 2024). "Moreover, increased USP3 transcriptionally modulated by Smoothened (Smo) reduces Claspin polyubiquitination and proteasomal degradation, leading to activation of Claspin-dependent ATR-CHK1 signaling and radiation resistance of glioblastoma (GBM)." (PMID 36694209, 2023).
colorectal cancer (5 papers, 2017 to 2024). A primary or metastatic malignant neoplasm that affects the colon or rectum. "In colorectal cancer, loss of USP3 is significantly associated with a poor prognosis and distal metastasis." (PMID 37170124, 2023). "For example, USP3 depletion promotes the development of colorectal cancer through decreasing SMAD4 expression." (PMID 37980532, 2023).
osteosarcoma (4 papers, 2024 to 2026). A usually aggressive malignant bone-forming mesenchymal neoplasm, predominantly affecting adolescents and young adults. "Through in vitro cell proliferation, colony formation, migration, wound healing and invasion assay, we found that downregulation of USP3 inhibited the proliferation, migration and invasion of osteosarcoma cells." (PMID 38531846, 2024). "As shown in osteosarcoma cells, overexpression of USP3 decreased EphA2 ubiquitination and stabilized EphA2 protein, whereas USP3 depletion enhanced ubiquitin-mediated EphA2 degradation." (PMID 39596256, 2024). "In addition, USP3 promoted proliferation and metastasis of osteosarcoma cells by enhancing in vitro EphA2-mediated PI3K/AKT signaling pathway and in vivo tumor growth." (PMID 39596256, 2024). "However, the role of USP3 in osteosarcoma (OS) remains poorly understood." (PMID 38531846, 2024).
esophageal squamous cell carcinoma (3 papers, 2021 to 2024). Esophageal squamous cell carcinoma (ESCC) is a type of esophageal carcinoma (EC) that can affect any part of the esophagus, but is usually located in the upper or middle third. "And study revealed that USP3 promotes the proliferation and metastasis of esophageal squamous cell carcinoma by stabilizing Aurora A." (PMID 38531846, 2024). "USP3 acts as a deubiquitinase of Aurora A to promote metastasis of esophageal squamous cell carcinoma." (PMID 37980532, 2023). "Here, we report that ubiquitin specific peptidase 3 (USP3) promotes proliferation and metastasis of esophageal squamous cell carcinoma (ESCC) cells by mediating deubiquitination of Aurora A. Analysis of human clinical samples indicated that USP3 and Aurora A are highly expressed in ESCC." (PMID 34758762, 2021).
leukemia (3 papers, 2019 to 2024). A malignant (clonal) hematologic disorder, involving hematopoietic stem cells and characterized by the presence of primitive or atypical myeloid or lymphoid cells in the bone marrow and the blood. "Even though we induced HL-60 cell differentiation by TPA treatment, USP3 depleted HL-60 cells inhibited leukemia cell differentiation, indicating that USP3 promotes leukemia cell differentiation." (PMID 31700696, 2019). "Taken together, our data indicate that USP3 promotes TPA-mediated leukemia cell differentiation via regulating H2AK119ub levels." (PMID 31700696, 2019). "Oncomine database also showed that level of USP3 decreased in various types of leukemia including AML." (PMID 31700696, 2019). "The human protein atlas showed that decreased expression of USP3 has a poor prognosis in urothelial cancer patients thus might act as a tumor suppressor in leukemia and urothelial cancer." (PMID 31700696, 2019). "The knockdown of USP3 inhibited TPA-induced leukemia cell differentiation via regulating H2AK119ub." (PMID 31700696, 2019). "Altogether, USP3 promoted leukemia cell differentiation via regulating H2AK119ub." (PMID 31700696, 2019). "A new mechanism of leukemia cell differentiation, regulation of H2A119ub by USP3, was demonstrated." (PMID 31700696, 2019). "However, USP3 depleted cells inhibited TPA-mediated leukemia cell differentiation and were compared with control cells." (PMID 31700696, 2019). "In addition, we revealed that depletion of USP3 inhibits TPA-mediated leukemia cell differentiation q-PCR and FACS analysis." (PMID 31700696, 2019). "Therefore, our study indicated that USP3-mediated deubiquitination at H2AK119 may have a therapeutic potential in leukemia cell differentiation." (PMID 31700696, 2019). "Therefore, USP3 may counteract to PRC1 complex to regulate cancer development including leukemia via removal H2AK119ub." (PMID 31700696, 2019). "It was found that USP3 decreased H2AK119ub levels in TPA-treated HL-60 cells, resulting in inducing leukemia cell differentiation." (PMID 31700696, 2019). "Furthermore, it is suggested that USP3 may counteract the effects of the PRC1 complex, potentially promoting leukemia cell differentiation, including in cases of leukemia, by removing the H2AK119ub modification." (PMID 39048945, 2024). "However, the association between USP3 and TPA-mediated leukemia cell differentiation has not been reported yet." (PMID 31700696, 2019). "However, USP38 levels did not change in TPA-treated HL-60 cells, indicating that USP3 and UPS35 were involved in leukemia cell differentiation." (PMID 31700696, 2019).
embryonic carcinoma (2 papers, 2021 to 2024). "Loss of another class of DUB, ubiquitin-specific peptidase 3, in human embryonic carcinoma cells results in a decrease in protein levels of Oct4." (PMID 38727276, 2024). "To elucidate the role of USP3 in embryonic stem cells, we generated single-cell-derived USP3 knockout clones in a human embryonic carcinoma cell line (NCCIT)." (PMID 34070420, 2021). "Our findings highlight the importance of USP3 in regulating Oct4 protein level in human embryonic carcinoma cells and human embryonic stem cells." (PMID 34070420, 2021).
gallbladder cancer (2 papers, 2024 to 2025). "In gallbladder cancer, USP3 stabilizes DNM1L by deubiquitination, inhibiting its proteasomal degradation." (PMID 41301681, 2025).
glioma (2 papers, 2020 to 2022). A benign or malignant brain and spinal cord tumor that arises from glial cells (astrocytes, oligodendrocytes, ependymal cells). "These evidences indicate that lncRNA HOXA‐AS3 can regulate the expression of USP3 in glioma through miR‐455‐5p." (PMID 32918360, 2020). "Other examples of the ceRNA-miRNA-mRNA axis in glioma include the lncRNA HOXA-AS3/miR-455-5p/USP3 axis, which promotes malignancy in GBM, and the Linc00152/miR-103a-3p/FEZF1 axis known to enhance malignancy in glioma stem cells (GSCs)." (PMID 36009578, 2022). "We further found that USP3 expression was positively correlated with lncRNA HOXA‐AS3 expression and negatively correlated with miR‐455‐5p expression in glioma tissues." (PMID 32918360, 2020).
lymphopenia (2 papers, 2015 to 2024). Reduction in the number of lymphocytes. "Indeed, a clear pathological manifestation of Usp3 deletion in mice is progressive lymphopenia upon aging." (PMID 26442100, 2015).
renal cell carcinoma (2 papers, 2023 to 2024). "Among the screened proteins, we found WDTC1 was significantly downregulated in KIRC, indicating that WDTC1 may be an interacting protein of USP3 in renal cell carcinoma." (PMID 37980532, 2023).
viral infection (2 papers, 2022 to 2023). "In addition, viral infection induces USP3 interaction with MDA5 to catalyze the removal of K63-linked ubiquitin chains, thus limiting sustained activation of MDA5 signaling." (PMID 35795661, 2022). "upon viral infection or ligand stimuli, USP3 interacts with the CARD domain of RIG‐I and cleaves Lys63‐linked Ub on RIG‐I. However, the detailed mechanism by which USP3 governs RIG‐I in vivo remains unclear." (PMID 37888853, 2023).
Autoimmunity (1 paper, 2021). The occurrence of an immune reaction against the organism's own cells or tissues. "Interestingly, multiple deubiquitinating enzymes, such as USP3, USP38 or DUBA, negatively regulate type I IFN response, and dysfunction of the ubiquitin pathway has been previously linked to autoimmunity." (PMID 33573268, 2021).
brain cancer (1 paper, 2023). A primary or metastatic malignant neoplasm affecting the brain. "We found that USP3 was highly expressed in cancers, including brain cancer, compared to normal tissues." (PMID 37170124, 2023). "To further interrogate the role of USP3 in brain cancer, we used the Cancer Cell Line Encyclopedia (CCLE) (RNA-seq) dataset to evaluate the expression of USP3 in different types of cancer." (PMID 37170124, 2023).
cardiomyopathy (1 paper, 2025). A disease of the heart muscle or myocardium proper. "The cardiomyopathy-associated targets were Dnmt1, Hdac1, Dot1l, Setd5, Nsd2, Usp3, Bap1, Prkca, Prkcb, Crebbp and Clock: 11 out of 81 (13.6% of total targets)." (PMID 40076868, 2025).
cholangiocarcinoma (1 paper, 2025). A carcinoma that arises from the intrahepatic biliary tree (intrahepatic cholangiocarcinoma) or from the junction, or adjacent to the junction, of the right and left hepatic ducts (hilar cholangiocarcinoma). "This review synthesizes current knowledge on six USP members—USP1, USP3, USP8, USP9X, USP21, and USP22—and delineates their context-dependent roles across cholangiocarcinoma and GBC subtypes." (PMID 41301681, 2025).
colon cancer (1 paper, 2017). "The correlation of USP3, SMAD4 and miR-224 was also verified in GSE29623, a GEO dataset containing mRNA and miRNA expression profiles of 65 colon cancer specimens." (PMID 28655924, 2017).
ductal carcinomas (1 paper, 2007). "The genes encoding proteins involved in ubiquitin-mediated proteolysis, such as USP3, RKHD2 and TTC3, and nuclear components, such as DTL, GLCC11, TTC14, FAM54A, HIST1H3B, were upregulated in ductal carcinomas." (PMID 17389037, 2007).
heart failure (1 paper, 2015). Inability of the heart to pump blood at an adequate rate to meet tissue metabolic requirements. "Interestingly, an intergenic SNP 58 kB upstream from USP3 (rs10519210) was the strongest SNP associated with heart failure in a GWAS from the CHARGE consortium." (PMID 26540294, 2015).
inflammatory bowel disease (1 paper, 2023). A spectrum of small and large bowel inflammatory diseases of unknown etiology. "Notably, three of these genes (CEPT1, PHLPP1, USP3) were reported to directly or indirectly link to inflammatory bowel disease through experimental or bioinformatics methods." (PMID 38201909, 2023).
lymph node metastasis (1 paper, 2019). "A significant relationship was observed between elevated USP3 expression and differentiation, AJCC stage and lymph node metastasis." (PMID 31234902, 2019).
periodontitis (1 paper, 2024). An acute or chronic inflammatory process that affects the tissues that surround and support the teeth. "The TWAS indicated that five cross-trait genes, including CC2D2B (10q24.1), RP11-326C3.7 (11p15.5), USP3 (15q22.31), HERC1 (15q22.31), and AMFR (16q13), may be implicated in the interaction of circulating immune cells with periodontitis." (PMID 38536078, 2024).
prostate carcinoma (1 paper, 2024). A carcinoma that arises from epithelial cells of the prostate gland. "Our team will be interesting to further investigate the molecular mechanisms underlying the overexpression of the USP3-SMARCA5 axis in prostate cancer." (PMID 39500888, 2024). "Clinically, USP3 was significantly up-regulated in prostate cancer tissues and positively associated with SMARCA5 expression." (PMID 39500888, 2024). "Taken together, these data suggest that USP3 knockdown reduced long-term proliferation and survival of prostate cancer cells in vitro and in vivo." (PMID 39500888, 2024). "To further investigate USP3 function in prostate cancer, we knocked down USP3 in both PC3 and DU145 cells via lentiviral transduction using two different USP3 shRNAs." (PMID 39500888, 2024). "Taken together, these results indicate that USP3 is upregulated in prostate cancer, positively correlating with SMARCA5 expression." (PMID 39500888, 2024). "Here, we found USP3 was frequently upregulated in PCa and correlates with prostate cancer progression." (PMID 39500888, 2024). "In addition, we found USP3 is overexpressed in prostate cancer samples and GEO database and showed that high expression of USP3 is related to prostate cancer development." (PMID 39500888, 2024). "In addition, we found that USP3 expression is up-regulated in prostate cancer tissues and positively with SMARCA5 expression." (PMID 39500888, 2024). "USP3 knockdown inhibit proliferation and survival of prostate cancer cells in vitro and in vivo." (PMID 39500888, 2024). "So we asked whether USP3 interacted with SMARCA5 to play function in prostate cancer." (PMID 39500888, 2024). "In addition, USP3 knockdown also reduced proliferation in non-prostate cancer cells, suggesting that USP3 may be essential to proliferation in many cell lines." (PMID 39500888, 2024). "Next, we further asked whether USP3 may as a potential target for prostate cancer therapy in vivo." (PMID 39500888, 2024). "Moreover, USP3 knockdown sensitizes cancer cells to DNA-damaging agents in xenograft models, suggesting that the USP3- SMARCA5 axis may provide new therapeutic targets for overcoming chemotherapy resistance in prostate cancer." (PMID 39500888, 2024). "Knockdown of USP3 impairs the DDR through SMARCA5 and results in increased sensitivity to Docetaxel treatment in prostate cancer cells." (PMID 39500888, 2024). "Herein, we report one critical target of USP3, SMARCA5 and the specific mechanism of USP3-mediated deubiquitination of SMARCA5 in Docetaxel-inducing DNA damage, suggesting that USP3 may be a promising target for anticancer therapy in prostate cancer." (PMID 39500888, 2024). "Moreover, a positive correlation between USP3 and SMARCA5 protein levels was observed in the prostate cancer human tissues supporting a role for the activity of the USP3-SMARCA5 axis in human prostate cancer cells." (PMID 39500888, 2024).
prostate tumor (1 paper, 2024). "To further test USP3 function in tumorigenesis, we employed an orthotopic prostate tumor model in which PC3 cells were injected subcutaneously into the nude mice." (PMID 39500888, 2024). "Clinically, USP3 levels are positively correlated with SMARCA5 in prostate tumors with high Gleason." (PMID 39500888, 2024). "To test the biological function of USP3-SMARCA5 axis in in vivo, we employed an orthotopic prostate tumor model in which PC3 cells were injected subcutaneously into the nude mice." (PMID 39500888, 2024). "In control mice, injection of PC3 cells resulted in formation of large prostate tumors, while comparable injection of PC3 cells transduced with either one of two different USP3 shRNAs indicated that USP3 knockdown decreased tumorigenesis." (PMID 39500888, 2024).